FASN (fatty acid synthase)
Diseases named in the same sentence as FASN in open-access papers (continued):
Sharing a sentence is not in itself a finding about the gene and the disease.
liver cancer (continued). "Our results are consistent with a report showing that blocking FASN with C75, a FASN inhibitor, reduces both OGT and O-GlcNAcylation levels in liver cancer cells." (PMID 38732103, 2024). "To address this question, we analyzed the protein level of FASN in liver cancer cells when SIAH1 was overexpressed or silenced and found that overexpression of SIAH1 decreased the expression of FASN, while knockdown of SIAH1 increased it." (PMID 39075049, 2024). "Contrary to SIX1 overexpression, SIX1 KO (knockout) in HepG2 liver cancer cells and SIX1 KD in MHCC97H and SMMC‐7721 liver cancer cells reduced mRNA expression of ACLY, ACC1, FASN, and SCD1, and protein expression of ACLY, FASN, and SCD1." (PMID 39258807, 2024). "In liver cancer, ACAT1 promotes lipid metabolism and tumor occurrence by stabilizing FASN through the acetylation of GNPAT." (PMID 39247186, 2024). "And the mRNA levels of ADRM1 and UCHL5 presented a direct correlation in normal and liver cancer specimens, as well as ADRM1 and FASN." (PMID 39075049, 2024). "In HepG2 liver cancer cell, acetate activated ACACA and FASN expression and increased de novo lipid synthesis under hypoxia, thus promoting cell survival." (PMID 35057851, 2022). "Furthermore, fatty acid synthase (FASN), a key enzyme in fatty acid biosynthesis, also participates in regulating liver cancer progression under elevated O‐GlcNAcylation levels." (PMID 41394960, 2025). "In our study, we confirmed that FASN could positively regulate FSCN1 and determined that FASN could promote filopodia formation in human liver cancer cells by regulating FSCN1." (PMID 39075049, 2024). "Although studies on FASN mostly focus on its regulation of lipid metabolism, its promotion of liver cancer transfer is not entirely dependent on it, and targeting FASN as a monotherapy has still shown limited efficacy." (PMID 39075049, 2024). "In terms of clinical protein expression correlation, the protein levels of SIAH1 and FASN exhibited a directly negative correlation in normal and liver cancer specimens." (PMID 39075049, 2024). "To confirm whether FSCN1 was involved in filopodia formation and cell movement regulated by FASN, we transfected Myc-tagged FSCN1 into FASN-silenced liver cancer cells." (PMID 39075049, 2024). "To explore whether UCHL5 acts as an upstream deubiquitinating enzyme for FASN in human liver cancer cells, we first analyzed the roles of UCHL5 in the regulation of FASN protein level in HepG2 and Huh7 cells." (PMID 39075049, 2024). "Furthermore, we found that SKP2 is one of the genes downregulated by the FASN inhibitor TVB3664 in in vitro and in vivo models of liver cancer." (PMID 39064589, 2024). "Moreover, visfatin and resistin increase cell viability, invasion, lipogenesis, fatty acid synthase (FASN) protein levels, MMP-9 activity, as well as Akt and ERK phosphorylation in liver cancer cells." (PMID 36670988, 2023). "Our previous study demonstrated that FASN was overexpressed in liver cancer tissues and cells, and the data indicated that FASN may be closely associated with liver cancer metastasis; however, the underlying molecular mechanism of FASN in liver cancer metastasis has not yet been identified." (PMID 32699531, 2020). "In the current study, silencing of FASN, FSCN1 or SPTBN1 expression in liver cancer cells led to changes in the mRNA expression of EMT-associated markers, E-cadherin, N-cadherin, vimentin and transcription factors Snail and Twist, and altered the protein expression of MMP-2 and MMP-9." (PMID 32699531, 2020). "Recent studies revealed that FASN directly regulates FSCN1 which participates in the formation of filamentous pseudopodia, lamellar pseudopodia, and microspines and the coding of cytoskeletal proteins, thus promoting the migration and invasion of liver cancer cells." (PMID 39075049, 2024).
liver cancer (continued). "On the contrary, FASN was not required in c-Met/β-catenin-driven liver cancer development, suggesting that tumors might be either addicted to or independent from FASN activity depending on the nature of oncogenes used." (PMID 33182674, 2020). "Furthermore, co-precipitation and co-localization of FASN with FSCN1 and SIPA1 in liver cancer indicated that FASN may mediate tumor metastasis via the PI3K/NF-κB/MMPs signaling pathway through interactions with FSCN1 or SIPA1." (PMID 32699531, 2020). "Previous studies have demonstrated the role of FASN in HCC, with higher expression in liver cancer tissues compared to non-tumoral tissues." (PMID 39332525, 2024). "Notably, G6PD, FASN and LPIN1 are upregulated in HCC compared with non-tumor livers in both HCC cohorts while ETFDH is downregulated, highlighting the likely role of lipid metabolism and PPP pathways in liver cancer." (PMID 37301960, 2023).
bladder cancer (40 papers, 2018 to 2025). "In various cancers, FASN is associated with high tumor grade and poor prognosis, and it has been suggested to contribute to the growth and invasion of bladder cancer." (PMID 41427247, 2025). "FASN was associated with immune cell infiltration in bladder cancer, and FASN inhibition promoted the sensitivity of tumors to ICI therapy." (PMID 38302980, 2024). "Reduction in level of a crucial fatty acid synthase (FASN) by GA during de novo lipid synthesis was associated with inhibition of the invasive activity of human bladder cancer cells." (PMID 32823607, 2020). "Meanwhile, the overexpression of FASN is linked to poor survival and drug resistance in breast, prostate and bladder cancers." (PMID 33118286, 2020). "A recent study identified that simvastatin (HMGCR inhibitor) use can reduce bladder cancer risk, and the FASN inhibitor TVB-2640 is currently being examined in different phase II clinical trials, although it is not currently approved as an independent cancer treatment." (PMID 40643470, 2025). "Moreover, we confirmed in this study previously reported results showing the elevated activity of FASN and the upregulation of gene encoding FASN in human bladder cancer." (PMID 29396722, 2018). "Furthermore, emerging data suggest that overexpression of the FASN is associated with tumor aggressiveness and migratory capacity of bladder cancer cells, as well as with resistance to chemotherapy." (PMID 29396722, 2018). "Taken together, these findings demonstrate that 3‐IAA binds to AhR and downregulates FASN transcription, thereby regulating ferroptosis in bladder cancer by disrupting the ratio of MUFAs to PUFAs." (PMID 40557796, 2025). "Mechanistically, 3‐IAA activates the aryl hydrocarbon receptor (AhR), which in turn downregulates fatty acid synthase (FASN) transcription in bladder cancer cells." (PMID 40557796, 2025). "Fatty acid synthase (FASN) is overexpressed in bladder cancer, catalyzing the synthesis of long-chain fatty acids from acetyl-CoA to provide lipid building blocks for tumor cell proliferation." (PMID 41438986, 2025). "The efficacy and safety of TVB-2640 in anti-tumor have been clinically investigated in phase I clinical trials 96, and FASN inhibitors were developed for bladder cancer." (PMID 41281744, 2025). "FASN-targeted drugs, such as orlistat, can reverse the resistance of bladder cancer models to programmed death-1 (PD-1) therapy." (PMID 40426972, 2025). "The use of FASN inhibitors for the treatment of bladder cancer is expected to have high efficacy and fewer toxic side effects." (PMID 41281744, 2025). "Indole‐3‐acetic acid (3‐IAA) derived from gut P. distasonis binds to AhR in bladder cancer cells and downregulates FASN transcription, thereby increasing sensitivity to ferroptosis and suppressing the development of bladder tumors." (PMID 40557796, 2025). "Studies have shown that FASN is one of the core genes of fatty acid metabolism in bladder cancer and is related to the efficacy of immune checkpoint therapy in bladder cancer." (PMID 41281744, 2025). "FASN independently predicts prognosis and regulates bladder cancer cell proliferation and metastasis via the Wnt/β-catenin pathway." (PMID 41153362, 2025). "The natural product cerulenin, an inhibitor of fatty acid synthase, can inhibit the proliferation and migration of bladder cancer cells." (PMID 40426972, 2025). "For lipid metabolism, FASN is highly expressed in bladder cancer, and FASN has a high targeting ability in bladder cancer." (PMID 41281744, 2025). "In bladder cancer, FASN (Fatty acid synthase) can acts as a central regulator of aerobic glycolysis, contributing to the metabolic switch in cancer and promoting tumor cell proliferation." (PMID 38332160, 2024). "In the beginning, we assessed FASN expression in 10 bladder cancer tissue specimens using western blotting (WB), revealing higher expression levels in tumors compared to adjacent noncancerous tissues." (PMID 39867879, 2024).
bladder cancer (continued). "In bladder cancer, FASN is a key regulator of fatty acid metabolism and is associated with immunotherapy." (PMID 38721154, 2024). "The fatty acid synthase (FASN) expression in bladder cancer is significantly upregulated and is regarded as an adverse prognostic factor for the recurrence and progression of bladder cancer." (PMID 37138354, 2023). "In bladder cancer, increased palmitoylation levels of FASN and PD‐L1 were correlated with cisplatin resistance." (PMID 36018061, 2023). "In this study, we established the GMII consisting of eight glutamine metabolism-related genes (ENPP1, GALK1, TALDO1, CYP19A1, FASN, AHCY, SLC7A9, and HSPG2), a high value of which is associated with poor prognosis in bladder cancer patients." (PMID 36911676, 2023). "Clinical studies also found PD-L1 palmitoylation in cisplatin-resistant bladder cancer cells, and inhibition of fatty acid synthase (FASN) inhibited PD-L1 palmitoylation and its expression." (PMID 37554324, 2023). "For example, our group innovatively demonstrated that metformin targeted Clusterin to regulate lipogenesis and inhibit the growth of bladder cancer cells through SREBP‐1c/FASN axis." (PMID 36052760, 2022). "By contrast, depletion of fatty acid level by knocking down of FASN in bladder cancer cells has been reported to suppress p‐AKT protein expression." (PMID 35243817, 2022). "For drugs targeting FASN, a phase II clinical trial revealed that temsirolimus show potential benefit in bladder cancer patients who are refractory to first line platinum-based chemotherapy." (PMID 35392075, 2022). "It activates the transcription of FASN, a major fat-generating gene, which promotes the growth of bladder cancer." (PMID 34539243, 2021). "A recent proteomics discovers that PD-L1 is FASN-dependent palmitoylation in bladder cancer cisplatin resistance and inhibition of FASN suppresses PD-L1 palmitoylation and expression." (PMID 34803494, 2021). "FASN catalyzing the terminal steps in the de novo biogenesis of fatty acids is correlated with low survival and high disease recurrence in patients with bladder cancer." (PMID 33604353, 2020). "A similar observation was made in human prostate and bladder cancer which presented higher FASN expression, confirming its wide application." (PMID 30619288, 2018). "FASN expression in bladder cancer patients also revealed increased FASN mRNA levels in the T1, T2, T3, and T4 groups, but not in Ta." (PMID 29396722, 2018). "FASN may be a potential therapeutic target for bladder cancer, and inhibition of FASN expression is expected to become a new method for the treatment of bladder cancer." (PMID 41281744, 2025). "Notably, the reduction of FASN expression decreases the ratio of MUFAs to PUFAs, thereby increasing ferroptosis sensitivity in bladder cancer cells." (PMID 40557796, 2025). "PD-L1 is highly palmitoylated in cisplatin-resistant bladder cancer cells, inhibition of fatty acid synthase (FASN) suppresses PD-L1 expression and palmitoylation, suggesting that the FASN-PD-L1 targeting therapy may be used for bladder cancer patients." (PMID 38762484, 2024). "Fatty acid synthase (FASN) is served as a prognostic marker of bladder cancer development." (PMID 37817081, 2023). "The clinical database suggested that higher FASN was associated with a poor prognosis in patients with bladder cancer, indicating that FASN might be the bladder cancer therapy target." (PMID 37587470, 2023). "Our study suggests that the inhibition of FASN by JorA may provide a basis for therapeutic strategies targeting bladder cancer lipid metabolism." (PMID 37587470, 2023). "Similar results were also observed after silencing FASN or TM4SF1 in bladder cancer cells." (PMID 35480865, 2022). "In addition, metformin, a commonly used drug for treating diabetes, has exerted potent inhibitory effect in tumor growth through targeting SREBP-1c and its downstream target FASN, thus inhibiting lipogenesis in bladder cancer." (PMID 35127296, 2022).
bladder cancer (continued). "Interestingly, the palmitoylation of FASN itself is also enhanced notably in cisplatin-resistant bladder cancer cells and 2-BP can suppress FASN expression in a dose-dependent manner potentially via inhibiting its palmitoylation." (PMID 34803494, 2021). "However, it should be emphasized that the level of SREBP1 mRNA is several-fold lower than that of SCD1 or FASN mRNA in human bladder cancer." (PMID 29396722, 2018). "Interestingly, the SCD1 mRNA levels at each stage of the disease were significantly higher than the FASN mRNA level in human bladder cancer." (PMID 29396722, 2018). "Furthermore, compared with other cancers, FASN is highly expressed in bladder cancer patients." (PMID 40557796, 2025). "However, it remains to be investigated whether a reduction in the palmitoylation levels of FASN and PD‐L1 can sensitize bladder cancer cells to cisplatin." (PMID 36018061, 2023). "Thus, it can be supposed that the level of SCD1 mRNA could be a more useful marker of human bladder cancer prognosis than the level of FASN mRNA, which is commonly studied in many cancer cells, including bladder cancer." (PMID 29396722, 2018). "This study identified five prognostic biomarker genes related to mitochondrial function and programmed cell death in bladder cancer (POLB, FASN, CASP9, VDAC2, and RHOT2) and preliminarily constructed a prognostic model based on these genes." (PMID 41427247, 2025). "Bioinformatics analysis of bladder cancer transcriptome data from the TCGA database revealed a significant positive correlation between FADS2 expression and SCD and FASN, molecules that reflect SREBP activity." (PMID 40682485, 2025). "Analysis of the TCGA database revealed a significant positive correlation between FADS2 expression in bladder cancer and the activity markers SCD and FASN, which reflect SREBP activity." (PMID 40682485, 2025). "FASN, MAP2 and BMP6 were highly expressed in bladder cancer, while GPC2, CNOT6L, GALNT12 and CARD10 were expressed at low levels in bladder cancer." (PMID 38218866, 2024). "In bladder cancer, metformin works by reducing the activity of sCLU, thus inhibiting tumor growth through the deactivation of the SREBP-1c/fatty acid synthase (FASN) axis." (PMID 38667280, 2024). "The expression of five of the eight GMII genes (TALDO1, AHCY, FASN, GALK1 and SLC7A9) in bladder cancer tissues was higher than that in normal tissues, while ENPP1, CYP19A1 and HSPG2 were down-regulated in tumor tissues (p < 0.05)." (PMID 36911676, 2023). "Moreover, pulldown assays and computer simulation technology were used to capture the molecules that may directly interact with JorA in bladder cancer cells, such as fatty acid synthase (FASN) and DNA topoisomerase 1 (Top1), which participate in the biological process of JorA inhibiting MIBC cells." (PMID 37587470, 2023). "In an in vitro experiment, we demonstrated that TM4SF1, FASN, and IMPDH1 were elevated in some bladder cancer cell lines." (PMID 35480865, 2022). "It is likely that the coordinated upregulation of FASN and SCD1, regulated by SREBP1, is contributing to the biosynthesis of fatty acids necessary for bladder cancer cell proliferation." (PMID 29396722, 2018). "Overall, these results suggest that not only the SCD1, FASN, and SREBP1, but probably also other genes, are downregulated in high-grade human bladder cancer." (PMID 29396722, 2018). "In our previous study, we showed that the activities of fatty acid synthase (FASN), ATP citrate lyase (ACLY), and the dehydrogenases of pentose phosphate pathway are significantly higher in human bladder cancer than in adjacent benign tissue." (PMID 29396722, 2018). "In this study, a novel prognostic model for bladder cancer was constructed based on POLB, FASN, CASP9, VDAC2, and RHOT2, which provided preliminary references for the prognostic evaluation of bladder cancer and subsequent studies related to its diagnosis and treatment." (PMID 41427247, 2025).
bladder cancer (continued). "High HER2 and FASN expression are associated with tumor recurrence and progression in bladder cancer, however the mechanistic details of HER2-FASN interactions have not been explored." (PMID 37779896, 2023). "Coordinated upregulation of FASN, ACLY, and pentose phosphate dehydrogenases that provide NADPH for palmitate biosynthesis, suggest that the rate of lipogenesis is also elevated in human bladder cancer." (PMID 29396722, 2018).